FHIP1B (FHF complex subunit HOOK interacting protein 1B)
Description:
Component of the FTS/Hook/FHIP complex (FHF complex). The FHF complex may function to promote vesicle trafficking and/or fusion via the homotypic vesicular protein sorting complex (the HOPS complex). FHF complex promotes the distribution of AP-4 complex to the perinuclear area of the cell.
Synonyms: FHIP; C11orf56; FAM160A2; KIAA1759; FLJ22665; DKFZP566M1046
Tractability: PROTAC: ubiquitination databases record sites on it.
Gene: Protein-coding gene on chromosome 11 (6,211,335 to 6,234,711, reverse strand). Ensembl gene ENSG00000051009.
Subcellular location (Human Protein Atlas): Mitochondria
Gene Ontology:
Molecular function: protein binding
Biological process: early endosome to late endosome transport; endosome organization; endosome to lysosome transport; lysosome organization; protein localization to perinuclear region of cytoplasm; protein transport along microtubule
Cellular component: FHF complex
Genetic constraint (gnomAD): Loss-of-function variants: 28 observed, 82.16 expected, observed/expected ratio (o/e) 0.34, 90% interval 0.25 to 0.47. The upper end of that interval is the gene's LOEUF score, 0.47, which puts it in group 2 of 6, group 1 being the genes least tolerant of losing a copy. Missense variants: 1,107 observed, 1,305.1 expected, observed/expected ratio (o/e) 0.85, 90% interval 0.81 to 0.89. Synonymous variants: 584 observed, 535.96 expected, observed/expected ratio (o/e) 1.09, 90% interval 1.02 to 1.17.
Homologues: Orthologues: chimpanzee FHIP1B (99% identical), macaque FHIP1B (98% identical), dog FHIP1B (96% identical), guinea pig FHIP1B (94% identical), mouse Fhip1b (94% identical), rat Fhip1b (93% identical), pig FHIP1B (93% identical), rabbit FHIP1B (91% identical), zebrafish fhip1b (54% identical), tropical clawed frog fhip1b (51% identical), Drosophila melanogaster CG3558 (31% identical), Caenorhabditis elegans C05D11.8 (22% identical). Paralogues in human: FHIP1A (39% identical), FHIP2A (17% identical), FHIP2B (17% identical).